WNT5A (Wnt family member 5A)
Diseases named in the same sentence as WNT5A in open-access papers (continued):
Sharing a sentence is not in itself a finding about the gene and the disease.
melanoma (continued). "An example of this is Wnt5a, which has been shown to correlate with poor prognosis and promote tumor cell invasion in melanoma, glioma, pancreatic, prostate and gastric cancer, however in breast cancer, Wnt5a has been better characterized as a tumor suppressor." (PMID 27589803, 2016). "Furthermore, both Wnt5a knockdown or PKC inhibition decreased the invasive potential of melanoma in vitro." (PMID 27417567, 2016). "Taking into account these findings, we set out to investigate whether WNT5A can regulate IL-6 expression and vice versa in a feedback loop in melanoma cells." (PMID 27191257, 2016). "In melanoma, Wnt5a-high expression is correlated with aggressiveness of the disease." (PMID 27571105, 2016). "Co-culture of WNT-5A-deficient melanoma cells with endothelial cells suppresses endothelial cell branching, whereas treatment of endothelial cells with exosomes isolated from WNT-5A-treated melanoma cells induces angiogenesis highlighting a proangiogenic role for WNT-5A." (PMID 26514730, 2016). "Two recent studies have demonstrated a link between IL-6 secretion and WNT5A expression in melanoma cells, suggesting that the combined therapeutic interference with this link might be beneficial for preventing disease progression and metastatic spread." (PMID 27191257, 2016). "In melanoma, Wnt5a expression was correlated strongly with both survival and time to metastasis." (PMID 27571105, 2016). "In melanoma cells, Wnt5a stimulates Akt-mTORC1 signaling through the Wnt/Ca+2 pathway." (PMID 27571105, 2016). "In the context of melanoma, WNT5A is an important player, whose increased expression could facilitate cell invasion and metastasis, thus promoting the progression of this disease." (PMID 27191257, 2016). "Indeed, some melanoma cell lines display a ‘neural precursor signature’, which intriguingly contains WNT5A and AXL." (PMID 25818589, 2015). "We also investigated whether therapeutic interventions using such regulators, along with Box-5, can impair melanoma cells that express high levels of WNT5A." (PMID 26393652, 2015). "The general consensus is that WNT5A expression in melanoma is mainly cytoplasmic." (PMID 26393652, 2015). "In addition Wnt5a enhances migration and invasion of tumor cells in melanoma and gastric cancer models." (PMID 26056085, 2015). "In this model, expressions of AXL and WNT5A define a distinct MITF‐negative population of melanoma cells, where MITF expression is not linked to BRN2 and the MAPK pathway and cells are MAPK pathway inhibitor unresponsive." (PMID 25818589, 2015). "Combined therapeutic approaches involving anti-IL-6 Ab (for antagonizing IL-6 signaling) and Box-5 (for antagonizing WNT5A signaling) might be beneficial for treating melanoma cells." (PMID 26393652, 2015). "As WNT5A is a prerequisite for migration and invasion in both normal and BRAFi-resistant melanoma cells, targeting WNT5A signaling provides a promising therapeutic option for melanoma disease management." (PMID 26393652, 2015). "Furthermore, by showing that knockdown of ROR2 can sensitize melanoma cells to PLX4720 therapy, they indicated a role for WNT5A in BRAFi resistance in melanoma cells." (PMID 26393652, 2015). "Furthermore, WNT5A protein expression was positively correlated with melanoma progression, tumor grade and patient outcome." (PMID 26393652, 2015). "The ability of WNT5A to inhibit MITF, a downstream target of β-catenin, may be one cause of resistance in BRAFi-treated melanoma patients, as MITF depletion can activate EGFR signaling, which can confer BRAFi resistance." (PMID 26393652, 2015). "For example, in malignant melanoma and pancreatic cancer, Wnt5a promotes tumor progression." (PMID 25779663, 2015). "Inhibition of WNT5A signaling in melanoma will make them less invasive." (PMID 26393652, 2015). "Moreover, the WNT5A-mediated effect on melanoma cell migration can be enhanced by the presence of syndecans 1 and 4, while WNT5A drives melanoma cell invasion and metastasis." (PMID 26393652, 2015).
melanoma (continued). "In addition, in a subset of melanoma cells, WNT5A has also been shown to induce β-catenin-mediated cell invasiveness via ARF-6." (PMID 26393652, 2015). "WNT5A mRNA was found to be significantly higher in melanoma specimens compared to normal specimens." (PMID 26393652, 2015). "Investigators extended their findings to clinical specimens as well when they demonstrated that 8 of 12 patients who relapsed while on BRAFi therapy showed increased positivity for WNT5A expression, clearly indicating the direct involvement of WNT5A in BRAFi resistance in melanoma patients." (PMID 26393652, 2015). "Indeed, mechanistic studies have revealed Wnt5a to promote melanoma cell migration and invasion, ultimately leading to disease metastases." (PMID 25339948, 2014). "In addition, increased Wnt5a expression levels in melanoma tissues as well as diminished levels of the soluble Wnt antagonist, Dkk-1, have been associated with an inferior clinical outcome in patients with advanced melanoma." (PMID 25339948, 2014). "Co-cultures of melanoma/endothelial cells showed that depletion of WNT5A in melanoma cells decreased endothelial cell branching, while stimulation of endothelial cells with isolated rWNT5A-induced melanoma exosomes increased endothelial cell branching in vitro." (PMID 24766647, 2014). "Furthermore, the effectiveness of the proposed methods is presented by a numerical example on the WNT5A network, which is related to melanoma." (PMID 24587766, 2014). "Non-canonical WNT5A signaling was implicated in the plasticity of melanoma cells expressed as phenotype switching from expression of ROR1 to ROR2 during hypoxia and acquisition of invasive characteristics." (PMID 24743024, 2014). "Therefore, branching assays were performed using the mouse endothelial cell line MS1 in co-cultures with HTB63 melanoma cells transfected with WNT5A siRNA and subsequently seeded on a Matrigel layer." (PMID 24766647, 2014). "Finally, gene expression data analysis of primary malignant melanomas revealed a correlation between WNT5A expression and the angiogenesis marker ESAM." (PMID 24766647, 2014). "In response to Wnt5a, several proteins, including a melanoma cell adhesion molecule, a Fzd receptor and cytoskeletal components (action microfilaments and a nonmuscle myosin, which are together called actomysin), become polarized in overlapping bands within the trailing edge of the migrating cells." (PMID 24944588, 2014). "This could partly be explained by the observations that; in vitro, WNT5A increases migration and invasion of malignant melanoma cells and in vivo, WNT5A signaling increases the spread and tumor formation of lung metastasis." (PMID 24766647, 2014). "Previous studies have correlated high WNT5A expression to poor prognosis in melanoma patients." (PMID 24766647, 2014). "Here we show, that malignant melanoma cell lines treated with recombinant (r)WNT5A induces a prominent, immediate release of immunomodulatory and pro-angiogenic factors IL-6, IL-8, VEGF and MMP2, while transcriptional activation of these genes remained unaffected." (PMID 24766647, 2014). "We, therefore, hypothesized that the inhibition of Wnt5a-mediated signaling would also augment immunotherapy efficacy in melanoma." (PMID 25339948, 2014). "In malignant melanoma and gastric cancer, Wnt5a actually promotes cancer progression." (PMID 22655072, 2012). "Thus, while Fzd5 expression is variable in non-melanoma skin cancer cells, its expression level in tumor-vessels is consistent with a role of this receptor in mediating Wnt5a-dependent inflammatory pathways, consistent with previous reports." (PMID 22384081, 2012). "Since Wnt5a increases migration and invasion of melanoma cells, these findings supported our idea that inhibition of Wnt5a signaling could be the mechanism by which SFRP3 decreased the migration and invasion of A2058 cells." (PMID 21494614, 2011).
melanoma (continued). "Consequently these data are in line with the previous assumption that SFRP3 inhibits migration in melanoma cells by inhibiting Wnt5a signaling." (PMID 21494614, 2011). "We found that recombinant SFRP3 could inhibit Wnt5a signaling, and that it inhibited melanoma cell migration and invasion in a Wnt5a-dependent manner." (PMID 21494614, 2011). "In peripheral non-neuronal systems, Wnt5a is implicated in inflammation of multiple chronic disorders, including rheumatoid arthritis, sepsis, atherosclerosis, melanoma, and psoriasis." (PMID 21857966, 2011). "Wnt5a was similarly invoked in aspects of cell polarity, including orienftation of cell division in the limb, convergent extension movements and cell shape in the Xenopus gastrula, and polarized migration in a melanoma cell line." (PMID 22216013, 2011). "In addition, Foxy5, a Wnt5a-derived hexapeptide (the same peptide as Box5 but differently modified) that can mimic Wnt5a-induced activities in malignant melanoma and in breast cancer cells, was also able to potentiate the neurotoxicity of Aβ/H2O2." (PMID 21857966, 2011). "Interestingly, there was no decrease in migration after treatment with SFRP3 in cells where Wnt5a had been knocked down, suggesting that SFRP3 inhibits migration in melanoma cells via inhibition of Wnt5a." (PMID 21494614, 2011). "In order to investigate possible mechanisms behind the decrease in migration and invasion induced by SFRP3 in A2058 cells, we investigated the expression of Wnt5a in these cells since Wnt5a is the only Wnt protein seen to increase migration and invasion of melanoma cells." (PMID 21494614, 2011). "Other work shows that WNT5A polarizes melanoma cells when a chemotactic gradient is present." (PMID 22216013, 2011). "While the precise mechanism of β-catenin independent Wnt signaling is less well understood, a great deal of research has focused on its role in melanoma metastasis following the initial discovery by microarray studies that Wnt5A was relatively overexpressed in more aggressive melanomas." (PMID 24281103, 2010). "Furthermore, the Wnt5A/Protein kinase C pathway was shown to mediate motility in melanoma cells via of an EMT." (PMID 19849855, 2009). "The potential role for increased Wnt-5a expression in malignant melanoma has recently been outlined as a study established that nuclear β-catenin levels are higher in primary tumours than in metastases and that low expression of nuclear β-catenin expression in primary tumours predicts poor survival." (PMID 19603030, 2009). "For instance, SWN but not NFB express the secreted glycoprotein WNT5A recently linked to metastases of OS and melanoma." (PMID 16168083, 2005). "Consequently, targeting WNT5A thereby inhibiting the secretion of related EVs might be a promising strategy for the treatment of melanoma patients." (PMID 37575250, 2023). "Moreover, we show that RNF43 could be a negative regulator of melanoma phenotype plasticity by targeting MITF-low/WNT5A-high melanoma cells." (PMID 34702444, 2021). "However, this impairment of WNT5A signaling appears to trigger a compensatory mechanism to maintain the invasive migration of BRAF wild‐type and BRAFV600 mutated melanoma cells treated with a BRAF inhibitor, through a RND3‐RhoA‐induced transition from a mesenchymal to an amoeboid mode of invasion." (PMID 33969605, 2021). "The fact that this activator restores the invasive property of WNT5A knockdown melanoma cells led us to conclude that Cdc42 signaling is essential for the WNT5A‐driven invasion of melanoma cells regardless of whether they invade via an amoeboid or mesenchymal mode of migration." (PMID 33969605, 2021). "Importantly, these results did not discriminate as to whether it was the expression or the phosphorylation status of MARCKS that is crucial for WNT5A-induced melanoma cell invasion." (PMID 32033033, 2020).
melanoma (continued). "Furthermore, the pro-inflammatory condition and Wnt5a signaling sustained autocrine positive feedback loops that included NF-kB, IL-6, STAT3 and other immune cells, causing an immunomodulatory effect on melanoma and conferred survival and therapeutic resistance." (PMID 32244473, 2020). "Since MARCKS is an actin-binding protein and phosphorylation of MARCKS could affect actin dynamics and thereby modulate melanoma cell motility and/or invasion, we further studied the molecular and subcellular events during WNT5A-mediated MARCKS phosphorylation in melanoma cells." (PMID 32033033, 2020). "Interestingly, the IL‐6/WNT5A positive feedback loop present in parental melanoma cells is lost during the development of BRAFi resistance in melanoma cells, and therefore, IL‐6 and WNT5A signalling cascades in these cells constitute independent regulatory events." (PMID 30582770, 2019). "However, we did not observe a significant reduction in Rac1‐GTPase activity in HTB63‐R cells treated with the combination of IL‐6 Ab and Box5, arguing against an essential role of Rac1 in the IL‐6‐ and WNT5A‐dependent invasive migration of BRAFi‐R melanoma cells." (PMID 30582770, 2019). "In addition, motility and invasion of melanoma cells is increased through WNT5A/FZD5 signaling." (PMID 29930766, 2018). "Furthermore, WNT5A was highly expressed in BRAF inhibitor (BRAFi)-resistant melanoma tumors." (PMID 29882812, 2018). "Considering the pro-metastatic role of both WNT5A and IL-6 in melanoma progression, a combined treatment that effectively inhibits the presently demonstrated WNT5A-IL-6 positive feedback loop is an attractive strategy to successfully impair melanoma cell invasion and metastasis." (PMID 27191257, 2016). "Indeed, an early microarray analysis for gene expression profiling demonstrated that Wnt5a could directly promote melanoma cell invasion and motility via inducing expression of Slug, which in turn promotes EMT gene expression in a PKC-dependent manner." (PMID 27895670, 2016). "To test our hypothesis that WNT5A and IL-6 could co-operate to accelerate melanoma metastasis, we first analysed whether their gene expression levels correlated with the invasive potential of melanoma cell lines." (PMID 27191257, 2016). "Furthermore, we demonstrated the ability of Box-5 (WNT5A antagonistic peptide developed in our laboratory) to inhibit extracellular lactate, suggesting that impairment of WNT5A signaling inhibits a glycolytic phenotype via inhibition of the PI3K-AKT pathway in melanoma cells." (PMID 26393652, 2015). "However, direct studies are warranted to investigate whether the inhibition of WNT5A signaling via Box-5 increases β-catenin expression, thereby sensitizing BRAFi-resistant melanomas to BRAFi therapy." (PMID 26393652, 2015). "However, the treatment of melanoma cells with Wnt5a led to a redistribution of CD146 into a polarised structure at the tail end of the cells; further assembly occurred between actin and myosin II with CD146 to form the Wnt5a-mediated receptor –actin – myosin polarity (WRAMP) structure." (PMID 25685061, 2015). "These subpopulations of ‘MITF‐negative’ cells, which are contained within a subset of melanoma cell populations originally identified by Hoek and colleagues, are characterized by the expression of the non‐canonical Wnt ligand WNT5A and the receptor tyrosine kinase AXL." (PMID 25818589, 2015). "As Wnt5a expression has been reported to be regulated by miRNAs in specific cellular contexts including prostate cancer, we hypothesized that regulation of protein translation or mRNA stability could be a mechanism for determining Wnt5a production levels in melanoma." (PMID 26029828, 2015). "Indeed, AXL+/WNT5A+ melanoma cells are resistant to MAPK pathway inhibitors and this might, at least in part, be due to the fact that the regulation of MITF expression is disconnected from BRAF." (PMID 25818589, 2015).
melanoma (continued). "With tumor progression, the expression of Wnt5a in the cytoplasm gradually increased, however, the expression of p16ink4a was reduced, indicating that overexpression of Wnt5a in the cytoplasm was positively correlated with the progress of the melanoma, as well as poor prognosis." (PMID 24944588, 2014). "Indeed, we could show that WNT5A induced activation of Cdc42 also in malignant melanoma Mewo cells and introduction of DN-Cdc42 and -Rac1 inhibited the WNT5A induced release." (PMID 24766647, 2014). "Gene expression profiling has indicated that WNT5A may be a marker of aggressive in melanomas." (PMID 24944588, 2014). "Furthermore, as a numerical example, we considered the WNT5A network, which is related to melanoma." (PMID 24587766, 2014). "Finally, a numerical example on the WNT5A network, which is related to melanoma, is presented." (PMID 24587766, 2014). "Interestingly, in certain types of cancers, such as hematological malignancies and colorectal carcinoma, WNT5A is inactivated and exerts a tumor suppressive function, while in other cancers, such as melanoma and gastric carcinoma, WNT5A is overexpressed and promotes tumor progression." (PMID 24260410, 2013). "In particular Wnt5A, which has been associated with enhanced invasiveness in melanoma was predominantly down-regulated in the B compared with the A class and conversely, MITF and melanoma differentiation antigens were prevalently expressed by the B class melanomas." (PMID 22537248, 2012). "Recent studies have suggested that Wnt5a signaling may regulate the peripheral inflammatory response in chronic disorders, including sepsis, rheumatoid arthritis, atherosclerosis, melanoma, and psoriasis." (PMID 22713358, 2012). "Therefore, we speculated that down-regulation of SFRP3 might affect the Wnt5a-driven aggressiveness of melanoma." (PMID 21494614, 2011). "Since Wnt5a increases migration and invasion of melanoma cells and SFRP3 and Wnt5a have previously been shown to antagonize each other, we hypothesized that one possible mechanism behind the inhibitory effects of SFRP3 on cell migration and invasion could be inhibition of Wnt5a signaling." (PMID 21494614, 2011). "Interestingly, other reports have instead suggested an oncogenic effect of Wnt5a primarily based on an upregulation in breast cancer cells (mRNA levels), gastric cancer (protein expression), melanoma (protein expression), lung cancer and prostate cancer (mRNA expression)." (PMID 22039506, 2011). "They used phenylmethimazole, an inhibitor targeting TLR-3, to decrease TLR-3 activity, expression and downstream signaling of Wnt5A both in vitro and in vivo, providing further evidence that targeting pathways that control Wnt5A may be useful for inhibiting melanoma progression." (PMID 24281103, 2010). "After noting that HSPGs are expressed at higher levels in melanoma cell lines of high metastatic potential, HSPGs were cleaved with heparinase III in these cell lines causing Wnt5A to accumulate in culture media concomitant with decreased downstream Wnt5A signaling in cells." (PMID 24281103, 2010). "Interestingly, transcriptional studies suggest that antagonism of Wnt/β-catenin signaling by Wnt5A may contribute to the downregulation of Wnt/β-catenin signaling observed with melanoma progression." (PMID 24281103, 2010). "This suggests that inhibition of canonical Wnt signalling may be important for progression of malignant melanomas and that the increased expression of Wnt-5a in high-grade tumours may serve to inhibit activation of the canonical signalling pathway and augment cancer growth." (PMID 19603030, 2009). "This APT1 phosphorylation promotes melanoma invasion in vitro and correlates with advanced tumor grade and metastasis, suggesting APT1 inhibition as a therapeutic strategy for Wnt5a-driven cancers." (PMID 40977744, 2025). "As WNT5A can stabilize YAP protein levels, inhibition of TCF12, WNT5A, or YAP blocks melanoma migration and metastasis." (PMID 38774408, 2024).